SOX2 (SRY-box transcription factor 2)
Diseases named in the same sentence as SOX2 in open-access papers (continued):
Sharing a sentence is not in itself a finding about the gene and the disease.
tumor (continued). "Thus, SOX2OT/miR-200/Sox2 played important roles in tumor progression and might be a useful marker for PC prognosis." (PMID 34760707, 2021). "Besides, the chemotherapy effect of irinotecan combined with CQ treatment on the tumor in the SW620 SOX2 KD group was better than that in the SW620 control group, suggesting that SOX2 knockdown may increase tumor chemosensitivity in vivo." (PMID 33953166, 2021). "The binding of CAGE to SOX2 may lead to enhanced tumor spheroid-forming potential in AGSR cells." (PMID 34113619, 2021). "Noteworthy, the CD8+/FOXP3+ TILs ratios in both tumor nests and stroma were consistently higher in tumors harboring negative expressions of NANOG and SOX2; however, significant associations were only reached between the tumoral CD8+/FOXP3+ ratio and both SOX2 and NANOG." (PMID 34201050, 2021). "Moreover, by comparative analysis within each tumor cell culture, of CD15high and CD15low subpopulations, it was reported that CD15high cells are also associated to higher SOX2 and PAX7 expression, and were detected in higher percentage in recurrent PAs as compared to the matched primary tumor." (PMID 32153500, 2020). "SOX2 expression has been associated with multiple tumor types; however, at the clinical level there is a lack of consensus as to whether it is a marker of good or poor prognosis." (PMID 32093282, 2020). "CSCs can be regulated by stemness markers (Oct4, Sox2, KLF4, c-Myc, Nanog, and others), signaling pathways (Hh, Wnt, Notch, TGF/BMP, Hippo, and other pro-survival pathways), extracellular factors (hypoxia, Tumor-associated macrophages, ECM, and vascular niches), and other factors." (PMID 33158118, 2020). "Given the presence of SOX2 in mHNcSCC and its association with local recurrence and metastasis, we speculate the TAZ-SOX2 axis as an important determinant of CSC stemness in this tumor." (PMID 32850316, 2020). "Moreover, SOX2 mediates tumor chemoresistance via the Wnt/β-catenin signaling pathway." (PMID 32439916, 2020). "We next validated whether SOX2 exhibited direct impact on tumor growth in vitro." (PMID 33158915, 2020). "However, Sox2 or VEGF knockdown greatly inhibited Snail-induced increasement of tumor growth." (PMID 32541667, 2020). "Furthermore, the acidic tumor microenvironment alters SOX2 in a VDR-dependent manner." (PMID 32900990, 2020). "Hence, we assumed that the elucidation of SOX2‐dependent pathways may identify novel therapeutic vulnerabilities in SCLC for the management of tumor regression." (PMID 32130794, 2020). "Additionally, there is ample evidence that SOX2 levels rise during tumor progression." (PMID 32998722, 2020). "This suggests that silenced SOX2 could reverse the tumour growth promoted by NF‐YA (P < 0.05)." (PMID 32954681, 2020). "SOX2 expression observed in both the nucleus and the cytoplasm of the cells within the TNs and the PTS of HNmMM tissue samples and its presence in HNmMM-derived primary cell lines may be associated with CSC maintenance and tumor growth." (PMID 32019273, 2020). "However, 3‐MA abolished the effect of gefitinib on decreasing the level of SOX2 in tumor tissues." (PMID 31823521, 2020). "Also, lineage-specific ablation of SOX2+ tumor cells or depletion of SOX2 expression could retard tumorigenicity by disconnecting the network system that favored generation of CSCs, thereby, preventing further tumor regrowth." (PMID 30517668, 2020). "Furthermore, an epigenomics analysis revealed that SOX2 can drive tumor heterogeneity in LUSC." (PMID 32598517, 2020). "However, the mechanisms by which SOX2 and other tumor-initiating cell markers are overexpressed in cancer remain unclear." (PMID 31844113, 2019). "Increasing the level of Hippo signalling in mouse embryos and adult mice led to an expansion of SOX2 stem cells that could generate new specialist cell types, but a further increase generated aggressive tumours that originated from the uncontrolled growth of SOX2 cells." (PMID 30912742, 2019).
tumor (continued). "The authors show Sox2 is expressed in undifferentiated cells at the tumour/stroma interface that are also positive for basal-like cell markers α6 and β1 integrin, which might be considered the “tumour stem cell compartment”." (PMID 31060263, 2019). "Furthermore, decreased levels of OCT4 and SOX2 were observed in TGIF2-silenced tumor cells, which could also be rescued by ectopically expressed TGIF2." (PMID 31871777, 2019). "The xenograft tumor growth might be related to the Oct3/4 and Sox2 expressions." (PMID 31126020, 2019). "Indeed, LncTCF7 downregulation in CSCs leads to a decreased expression of the pluripotent transcription factors Sox2, Nanog and Oct4, reduces tumor initiating capacity upon subcutaneous injection of nude mice and suppresses xenograft tumor growth and tumorigenic cell frequency." (PMID 29443889, 2018). "However, the tumour bulk was found to be YFP negative, suggesting that tumour cells had a different cell of origin to the mutation-sustaining SOX2+ cells." (PMID 28855316, 2018). "Hence we have investigated whether e-cigarette extracts can enhance tumor promoting properties similar to nicotine; we find that they can induce expression of Sox2 as well as mesenchymal markers and enhance migration and stemness of NSCLC cells." (PMID 30322398, 2018). "Furthermore, we found that the DsRed+ (Sox2+) cells acquired chemoresistance to 5-FU and oxaliplatin, and that Sox2+ cells exhibited slower growth activity in vitro, though they exhibited larger tumor formation in vivo." (PMID 30518951, 2018). "Since OIP5-AS1 is expressed at high level in undifferentiated tumor cells, we asked the question whether the promoter of OIP5-AS1 gene has possible binding motifs for stemness associated TFs (Yamanaka factors) MYC, KLF4, OCT4, SOX2, and NANOG." (PMID 29728583, 2018). "Therefore, we were hardly able to prove Sox2+ cells within the tumour tissue at all." (PMID 29158570, 2017). "First, there may be an increase in the number of SOX2-positive cells in the tumor population." (PMID 28388544, 2017). "In addition to increasing our understanding of tumor biology and the roots of cancer, Sox2 activation could be used as a tool to accelerate drug discovery for cancer treatment." (PMID 28191771, 2017). "In addition to determining how SOX2 levels change during tumor progression, it is essential to determine whether SOX2 levels correlate with clinical prognosis for cancer patients." (PMID 28388544, 2017). "We next used a xenograft model to test whether SOX2 knockdown reduces tumour growth in vivo." (PMID 28288641, 2017). "Moreover, in some tumors, SOX2 expression has been shown to increase during tumor progression." (PMID 28388544, 2017). "Moreover, Ad-ATF/SOX2 effectively inhibited tumor growth in a lung SCC xenograft mouse model." (PMID 29262545, 2017). "Interestingly, this variable expression of SOX2 across cells within the same tumor has been observed in multiple cancers and may influence their physiology in the section “SOX2 and Tumor-Initiating Cells/Cancer Stem Cells”." (PMID 28388544, 2017). "Thus, we suggest, wherever possible, that future efforts to associate SOX2 with cancer stem cells of a given type of tumor focus on those markers that do not change readily in response to changes in cellular condition." (PMID 28388544, 2017). "Again, we used nestin, Sox2, βIII-tubulin and S100β to assess the cell differentiation state and found all tissues exhibited relatively high numbers of cells expressing nestin and S100β, but low numbers of cells expressed βIII-tubulin and Sox2, as expected for this type of tumour." (PMID 27541285, 2017). "However, it is unclear whether the effect of MALAT1 on SOX2 in these tumor cells is direct or indirect." (PMID 28388544, 2017).
tumor (continued). "In summary, these data support a model in which high expression of SOX2—as a consequence of copy number variation—but also other so-far less well characterized mechanisms contribute to the pathogenesis of HNSCC by promoting tumor cell proliferation and survival." (PMID 28671620, 2017). "Thus far, only SRR2 has been reported to be active in SOX2-positive tumor cells." (PMID 28388544, 2017). "To evaluate whether SEC62 and SOX2 expression exerts any influence on lymphatic metastasis of HNSCCs, we analyzed the expression levels of both genes in the primary tumor and the lymph node metastases from all 65 HNSCC patients using immunohistochemical staining." (PMID 28002801, 2017). "In addition to the cell-based experiments, we used an EBC2 lung SCC xenograft nude mice tumor model to determine whether ATF/SOX2 suppresses tumor growth in vivo." (PMID 29262545, 2017). "Importantly, it was found that SS cultures contain a subpopulation of cells expressing high levels of CXCR4 that also express high levels stem cell markers (NANOG, OCT4, SOX2), and these cells have an increased tumor initiating capacity in xenographic mouse models." (PMID 28191313, 2017). "Furthermore, SOX2 inhibition induced genes related to EMT, which may cause tumor invasion and metastasis." (PMID 26846300, 2016). "However, the wide range of SOX2 activated tumor progression pathways may overcome the effects of this molecular alteration." (PMID 26540632, 2016). "The significant association, emerged from the multivariate analysis, between the increase in SOX2 mRNA expression in the primary tumor and the presence of lymph node metastasis, led us to further assess whether SOX2 regulates gene sets implicated in tumor growth and progression." (PMID 26540632, 2016). "Analyses of gene copy numbers were performed on DNA from paired non-tumorous and tumor tissue of the same patient in order to evaluate whether genomic variations in SOX2 may be associated with lung tumor development." (PMID 26780934, 2016). "Once this technology becomes available, it would be able to separate subpopulations presenting high activity or expression of both ALDH1 and SOX2 and could potentially represent tumor-propagating subpopulations better than the cell subset solely selected by ALDH1 activity." (PMID 27292183, 2016). "Since both Sox2 shRNA treated TRCs and scrambled shRNA treated TRCs emitted green fluorescence, we had to use Tg(kdrl:mCherry) zebrafish to visualize blood vessels (red color) and shRNA transfected tumor cell (green color) proliferation and metastasis simultaneously." (PMID 26787224, 2016). "Furthermore, inhibition of miR-125b or miR-20b induced MES-associated CD44 expression, but did not alter the levels of PN-associated SOX2 in these tumours." (PMID 27698350, 2016). "We also evaluated whether SOX2 rescued miR-371-5p's effects on tumor growth and metastasis in vivo." (PMID 25868860, 2015). "However, SOX2 high expression was found in 68/117 (58.1%) of tumor tissues." (PMID 28983346, 2015). "In addition, the downregulation of SOX2 expression correlated with a decrease in tumor cell proliferation, as indicated by the Ki-67 marker, which was maintained downregulated relative to uninduced cells even after removal of ZF598-DNMT3A expression for 10 days." (PMID 25684141, 2015). "Similarly, SOX2 expression became higher with increasing invasiveness of the tumor." (PMID 28983346, 2015). "Interestingly, SOX2 expression in BC is mostly confined to a minor subset of tumor cells and detectable at early stages of the disease as well as at relapse, suggesting that it is involved in BC stem cell biology and might represent a genetic driver event." (PMID 26498353, 2015). "However, when SOX2-deletion cells were transplanted into C57/Bl6 mice they remained tumor free." (PMID 25114775, 2014).
tumor (continued). "In contrast, in non-responder patients all primary tumours stained positive for Sox2 (22 patients); furthermore, there was a significant increase in Sox2 expression in the recurrent lesions (26 samples, since four of them recurred twice), compared with the matched primary tumours." (PMID 24178749, 2014). "In malignancy growing evidence reveals SOX2 to be a central regulator of a tumourigenic, stem cell-like subpopulation of tumour cells, frequently referred to as cancer stem cells (CSCs), which are found to be responsible for the proliferative and invasive capacities of most tumour types." (PMID 25156079, 2014). "The fact that the SOX2 positive cells only made up a small proportion of the whole tumor, suggests that these cells may display a more invasive phenotype than the surrounding tumor cells." (PMID 25010701, 2014). "Although the SOX2 protein is normally confined to the nucleus, we found that in the cancer cells, there was both nuclear and cytoplasmic expression, which may indicate abnormal accumulation of the protein in tumour cells." (PMID 25531390, 2014). "We then asked whether SOX2 antibodies correlated with SOX2 protein expression in tumor tissues." (PMID 24940116, 2014). "Sox2 is a good example of a gene involved in embryonic development whose expression is reactivated during tumor generation, as Sox2 is critical to maintain the pluripotent phenotype in embryonic stem cells (ESCs) and its expression is reactivated during tumor progression." (PMID 25414831, 2014). "The present study was designed to detect hTERC and SOX2 amplifications in OSSC exfoliative tumor cells and evaluate whether these two gene amplifications might serve as a supportive bio-marker for the non-invasive detection and diagnosis of oral and oropharyngeal SCC." (PMID 24410919, 2014). "Thus, Sox2 appears to promote castration resistance via mechanisms that do not involve the re-expression of embryonic stem cell Sox2-target genes or increases in rare tumor stem/initiating cell populations." (PMID 23326489, 2013). "SOX2 could serve as a valuable prognostic marker in these rare tumor entities." (PMID 23544055, 2013). "Thus, LAPC-4 cells do not efficiently form tumors in castrated male nude murine hosts, allowing us to test whether Sox2 expression was sufficient to promote castration-resistant tumor formation." (PMID 23326489, 2013). "In the tumor invasive front (the leading edge), a significant association was identified between the expression of SOX2 and OCT4 (Spearman correlation coefficient, 0.188; P = 0.038), as well as SOX2 and Nanog expression (Spearman correlation coefficient, 0.223; P = 0.014)." (PMID 23424657, 2013). "In addition it could be demonstrated that inhibition of proliferation is associated with downregulation of the known stem cell factors NANOG, POU5F1 and SOX2 in tumor cells." (PMID 23969837, 2013). "Decreased expression of CD44 and SOX2 might reduce the oncogenic potential of the tumor cells." (PMID 24156782, 2013). "Thus, the biological effects of Sox2 in cancer cells are likely to be tumor type-specific." (PMID 23815808, 2013). "Consequently, targeting of SOX2 is a promising strategy for tumor therapy." (PMID 22615765, 2012). "Moreover, both populations exhibited dramatic reductions in their ability to form neurospheres when Dox was added, arguing that CD133− DAOY cells as well as the putative tumor-initiating population of CD133+ DAOY cells must carefully regulate SOX2 levels to support their self-renewal." (PMID 22937156, 2012). "Finally, we showed that SOX2 expression correlated to more advanced tumor stages of T3–T4." (PMID 22912670, 2012). "Importantly, prestimulation of BM mononuclear cells from MGUS patients with the SOX2 peptide library is translated into the inhibition of clonogenic growth, suggesting that targeting SOX2 immunity may restrain tumor expansion." (PMID 22567028, 2012).
tumor (continued). "Therefore, relative Sox2 expression and functions within the tumor-CSCs may be a major determinant in EGFR-targeted therapy against NSCLCs." (PMID 23009336, 2012). "C-MYC may function as an oncogene and OCT4, KLF4, NANOG and SOX2 as tumor suppressors." (PMID 21982273, 2011). "Indeed, the oncogenic/tumor suppressor potential of SOX2 seems to be cell-type dependent." (PMID 21919124, 2011). "Flow cytometry analysis identified tumor cells based on forward light scatter (FSC) and side light scatter (SSC), followed by gating for SOX2 expression, a marker of stem-like properties." (PMID 41596406, 2026). "Loss of SMAD4 leads to enhanced H3K27ac deposition, aberrant SOX2 activation, and increased LUSC tumor cell proliferation." (PMID 42189071, 2026). "SOX2-positive tumor cells in primary human SCC, including cSCCs, were especially seen at the TSI, which is in line with the SOX2 expression pattern in our EB-cSCC cohort." (PMID 41189680, 2026). "We also examine how transcriptional and oncogenic regulators, including SOX2, MYC, and androgen receptor signalling, reprogramme sialyltransferase expression to produce tumour-specific sialoglycan profiles." (PMID 42132142, 2026). "Key members such as SOX2, SOX4 and SOX9 notably influence the malignant progression of NSCLC by regulating processes including tumor stemness, EMT, cell proliferation, apoptosis, invasion, metastasis and drug resistance." (PMID 41268614, 2026). "Specific inhibitors of IL-17RA signaling, such as the STAT3 inhibitor Stattic, reduced the expression of CD133, LGR5, ALDHA1, SOX2 and c-MYC, as well as tumor sphere formation in SW620 cells." (PMID 41438576, 2026). "The results showed minimal SOX2 and Ki67 positive cells, suggesting that the transplantation of in vivo-induced NILB-hiPSCs in the TDP-43-injected monkeys has low tumor-forming potential and high safety." (PMID 41362729, 2026). "Emerging evidence suggests that SOX-2 and EZH-2 play critical roles in salivary gland carcinogenesis, being related to tumor cell stemness potential, along with accelerated tumor progression and unfavorable clinical outcomes." (PMID 42029612, 2026). "Immunoblotting of three representative pairs confirmed increased SOX2 and LPCAT1 protein in tumor relative to matched normal tissue, with GAPDH as loading control." (PMID 41358198, 2025). "RNAscope analysis of 3 human CPPs showed co-expression of SOX2 and NOTCH target HES5 in a small fraction of tumor cells." (PMID 40128799, 2025). "The prognostic analysis suggests the potential important role of SOX2 and NTRK2 in NPC tumor progression, prompting further exploration of their function in NP cells." (PMID 40133476, 2025). "The interplay between cellular plasticity and stemness factors like OCT4, SOX2, and NANOG enables PCa cells to adapt under therapeutic pressure, contributing to tumor heterogeneity, EMT activation, and drug resistance." (PMID 40722714, 2025). "The expression of SOX12 was higher in the tumor cell subgroup compared to normal subgroup, whereas other SOX transcripts, including SOX2, SOX5, SOX9, SOX11, and SOX15, had low expression in tumor clusters." (PMID 40593465, 2025). "Thus, high expression of POU5F1, ALDH1, and SOX2 in enzalutamide-resistant cells and samples from androgen deprivation therapy-treated patients may signify a stem-cell-like state, granting tumor cells significant lineage plasticity and enabling them to evade immune and targeted therapies." (PMID 40821114, 2025). "Recent studies have also highlighted the role of TGLI1 in activating SOX2 within BrM, promoting cancer stem cell (CSC) traits, and modifying the tumor microenvironment through astrocyte activation enhancing tumor growth and metastatic establishment." (PMID 40016470, 2025).